OSBPL2 (oxysterol binding protein like 2)
Description:
Intracellular transport protein that binds sterols and phospholipids and mediates lipid transport between intracellular compartments. Increases plasma membrane cholesterol levels and decreases phosphatidylinositol-4,5-bisphosphate levels in the cell membrane. Exhibits strong binding to phosphatidic acid and weak binding to phosphatidylinositol 3-phosphate. Binds cholesterol, dehydroergosterol, 22(R)- hydroxycholesterol and 25-hydroxycholesterol (in vitro). In conjunction with PLCB3, it may contribute to the control of keratinocyte proliferation and differentiation, probably through the regulation of the ERK pathway and the cell cycle. Involved in angiogenic signaling pathways such as VEGFR2 in endothelial cells. Controls LDL-cholesterol plasma membrane delivery, focal adhesion kinase (FAK) activation and PI(4,5)P2 generation, enhancing cell adhesion.
Synonyms: ORP-2; KIAA0772; ORP2; DFNA67; DIDA; DNFA67; LOC105369209
Tractability: Small molecule: a structure with a bound ligand is known. Antibody: UniProt places it where antibodies can reach, with high confidence; its Gene Ontology location is reachable by antibodies, with medium confidence. PROTAC: ubiquitination databases record sites on it; its protein half-life has been measured.
Gene: Protein-coding gene on chromosome 20 (62,231,922 to 62,296,213, forward strand). Ensembl gene ENSG00000130703.
Subcellular location: Cytoplasm, cytosol; Lipid droplet; Cell membrane; Cell projection, stereocilium
Subcellular location (Human Protein Atlas): Cytosol
Pathways (Reactome):
Metabolism: Synthesis of bile acids and bile salts
Gene Ontology:
Molecular function: cholesterol binding; cholesterol transfer activity; phosphatidylinositol transfer activity; phosphatidylinositol-4,5-bisphosphate binding; protein binding; sterol transfer activity; lipid binding
Biological process: cholesterol transport; intracellular cholesterol transport; phospholipid transport; plasma membrane organization; protein homotetramerization; regulation of synaptic vesicle priming; bile acid biosynthetic process; intermembrane lipid transfer; regulation of presynaptic cytosolic calcium ion concentration
Cellular component: cytoplasmic side of plasma membrane; cytosol; glutamatergic synapse; lipid droplet; plasma membrane; perinuclear endoplasmic reticulum; cytoplasm; presynaptic active zone cytoplasmic component; stereocilium
Genetic constraint (gnomAD): Loss-of-function variants: 17 observed, 54.56 expected, observed/expected ratio (o/e) 0.31, 90% interval 0.21 to 0.47. The upper end of that interval is the gene's LOEUF score, 0.47, which puts it in group 2 of 6, group 1 being the genes least tolerant of losing a copy. Missense variants: 437 observed, 601.35 expected, observed/expected ratio (o/e) 0.73, 90% interval 0.67 to 0.79. Synonymous variants: 209 observed, 231.86 expected, observed/expected ratio (o/e) 0.9, 90% interval 0.8 to 1.01.
Gene-disease validity (ClinGen):
ClinGen rates the evidence that OSBPL2 causes each of these diseases.
nonsyndromic genetic hearing loss (autosomal dominant): Moderate. A disease characterized by hearing loss that is not part of a larger syndrome.
Homologues: Orthologues: chimpanzee OSBPL2 (99% identical), macaque OSBPL2 (94% identical), guinea pig OSBPL2 (93% identical), mouse Osbpl2 (90% identical), pig OSBPL2 (88% identical), dog OSBPL2 (87% identical), rat Osbpl2 (85% identical), tropical clawed frog osbpl2 (73% identical), zebrafish osbpl2b (71% identical), zebrafish osbpl2a (68% identical), rabbit OSBPL2 (59% identical), Drosophila melanogaster CG3860 (46% identical), and 1 more. Paralogues in human: OSBPL1A (67% identical), OSBPL6 (36% identical), OSBP (35% identical), OSBP2 (35% identical), OSBPL3 (35% identical), OSBPL7 (34% identical), OSBPL8 (24% identical), OSBPL5 (24% identical), OSBPL10 (21% identical), OSBPL9 (20% identical), OSBPL11 (20% identical).
Diseases named in the same sentence as OSBPL2 in open-access papers:
OSBPL2 is named in the same sentence as 24 diseases in open-access papers, as found by Europe PMC text mining. Sharing a sentence is not in itself a finding about the gene and the disease. The quoted sentences say what the papers report.
hearing loss (6 papers, 2015 to 2024). "Oxysterol-binding protein like 2 (OSBPL2) was identified as a novel causal gene for autosomal dominant nonsyndromic hearing loss." (PMID 31427568, 2019). "The frameshift mutation in OSBPL2, c.158_159delAA, co-segregated in the family and was only detected in patients with hearing loss." (PMID 30894143, 2019). "Oxysterol Binding Protein-like 2 (OSBPL2) has been identified as a causal gene for hearing loss." (PMID 39475791, 2024). "However, further research is necessary to clarify how OSBPL2 deficiency causes hearing loss." (PMID 25759012, 2015). "Among the contributors to PDT-EC we identified OSBPL2 and SYNE4, two relatively new hereditary hearing loss genes with a low publication profile." (PMID 35682719, 2022). "The association of OSBPL2 mutations with ADNSHL indicates a role of lipid metabolism in hair cell function, defining another functional category of proteins involved in hearing loss." (PMID 25759012, 2015). "For instance, a specific inherited condition characterized by tinnitus and hearing loss in humans is produced by mutations in the gene coding for OSBPL2 (oxysterol binding protein-like 2; MIM606731), so-called autosomal dominant hearing loss (DFNA67)." (PMID 38068993, 2023). "Osbpl2 was among 132 mRNAs with 3′UTRs predicted to contain potential target sites for miR-96, a microRNA whose mutations cause progressive hearing loss in mice and humans, but we found no upregulation of Osbpl2 in Mir96 mutant mice (diminuendo)." (PMID 25759012, 2015).
deafness (4 papers, 2015 to 2024). An inherited or acquired condition characterized by the complete loss of the ability to hear from one or both ears. "Whole genome sequencing identified a two-nucleotide deletion in OSBPL2 (c.158_159delAA) as the pathogenic variant for deafness in the family." (PMID 30894143, 2019). "Genetic analysis of a Chinese autosomal dominant deafness family identified a frameshift mutation in OSBPL2 gene (c.153_154delCT) providing the first evidence that OSBPL2 is associated with the occurrence of non-syndromic deafness." (PMID 30894143, 2019). "In this study, a new frameshift mutation, c.158_159delAA (p.Gln53Arg fs*100) in OSBPL2 (NM_144498.2), was found in a family with hereditary late-onset non-syndromic deafness by whole genome sequencing, followed by confirmation with Sanger sequencing." (PMID 30894143, 2019). "A frameshift deletion in OSBPL2 (c.158_159delAA) was identified by whole genome sequencing as the pathogenic variant of a Mongolian family hereditary late-onset deafness." (PMID 30894143, 2019). "To identify the causal gene for deafness in this family, we applied whole genome sequencing analysis to pinpoint OSBPL2 (Oxysterol-binding protein-related protein 2) as the disease gene." (PMID 30894143, 2019). "Our finding expands the mutational spectrum of OSBPL2 and contributes to the pathogenic variant list in genetic counseling for deafness screening." (PMID 30894143, 2019). "Our study and the recent description of another frameshift mutation in a Chinese ADNSHL family identify OSBPL2 as a novel gene for progressive deafness." (PMID 25759012, 2015). "Our findings showed that Osbpl2–/– mice exhibited progressive deafness and demonstrated shortened cochleae and misaligned HCs as well as morphological abnormalities of the kinocilia of HCs." (PMID 35041619, 2022). "In our previous study, oxysterol-binding protein like 2 (OSBPL2, OMIM: 606731) was identified as a novel deafness-causative gene (DFNA67) in a large Chinese family." (PMID 35041619, 2022). "Subsequently, another frameshift mutation (c.141_142delTG) in the OSBPL2 gene was also found in a German NSHL family, further confirming that OSBPL2 is a new deafness gene." (PMID 30894143, 2019). "Our finding extends the pathogenic variant spectrum of OSBPL2 in autosomal dominant hereditary deafness (ADNSHL) and provides the genetic basis to include OSBPL2 in genetic counseling for deafness screening." (PMID 30894143, 2019).
Hypercholesterolemia (3 papers, 2020 to 2022). An increased concentration of cholesterol in the blood. "In addition to the expected phenotype of hearing loss, we found the obesity phenotypes with hypercholesterolemia in the OSBPL2 mutation Bama mini pig16." (PMID 34001864, 2021). "Recent studies have showed a linkage between OSBPL2/ORP2 and obesity-related disease: the regulation of LD lipolysis required OSBPL2/ORP215, and the OSBPL2-disruption resulted in hypercholesterolemia in miniature pig models." (PMID 34001864, 2021). "Knockout OSBPL2 bama miniature pigs have hypercholesterolemia, increase in adipocytes, with obesity phenotypes." (PMID 33382735, 2020). "The deletion of oxysterol binding protein-like 2 (OSBPL2), an intracellular lipid receptor, disrupted LD localization of the subunit COPBI, leading to lipid accumulation in larger LDs and hypercholesterolemia in zebrafish." (PMID 36119738, 2022).
Obesity (3 papers, 2020 to 2022). Accumulation of substantial excess body fat. "To summarize, according to the cooperative reaction of two pathways induced by activation of receptors SORT1 and OSBPL2, obesity can drive malignant obese PCa." (PMID 35164166, 2022). "Obesity will trigger PI4P ligands to inhibit the expression of receptor OSBPL2, resulting in the accumulation of fat and cholesterol in the downstream signaling pathway." (PMID 35164166, 2022). "A recent study reported that OSBPL2/ORP2 localizes to lipid droplets (LDs) and is associated with energy metabolism and obesity." (PMID 34001864, 2021). "The link between decreased OSBPL2 expression and obesity in an animal model is interesting given obesity is a known epidemiological risk factor for canine ACL rupture and two of the chromosome 24 CNVRs were deletions." (PMID 33382735, 2020). "In this study, we found that OSBPL2/ORP2 maintained β-catenin in the cytoplasm and promoted β-catenin translocation into the nucleus, indicating the underlying molecular mechanism by which OSBPL2/ORP2 and preadipocyte development are related to obesity." (PMID 34001864, 2021). "Deletion of OSBPL2/ORP2 markedly reduces β-catenin both in the cytoplasm and in the nucleus, promotes preadipocytes maturation, and ultimately leads to obesity-related characteristics." (PMID 34001864, 2021). "Our work presented a novel insight into the function of OSBPL2/ORP2, which may provide the potential target and therapeutic approach in the treatment of obesity-related metabolic disease." (PMID 34001864, 2021). "Altogether, we provide novel insight into the function of OSBPL2/ORP2 in the developmental progression of preadipocytes and suggest OSBPL2/ORP2 may be a potential therapeutic target for the treatment of obesity-related diseases." (PMID 34001864, 2021).
autosomal dominant deafness (2 papers, 2019 to 2025). "A mutation in oxysterol-binding protein-like 2 (OSBPL2) has been identified as the genetic cause of autosomal dominant nonsyndromic hearing loss (DFNA67, Online Mendelian Inheritance in Man No. 616340)." (PMID 40391522, 2025).
atherosclerosis (1 paper, 2019). A disease characterized by the build-up of fatty material and calcium deposition in the arterial wall resulting in partial or complete occlusion of the arterial lumen. "Interestingly, it was found that Apolipoprotein E (ApoE) knockout mice developed remarkable hyperlipedimia, atherosclerosis and hearing impairment, which might share the similar pathogenesis of OSBPL2 deficit in SNHL48." (PMID 31427568, 2019).
colorectal tumors (1 paper, 2024). "The future research direction of OSBPL2 as a secretory protein may be associated with exosomes acting on colorectal tumor microenvironment." (PMID 38267463, 2024). "However, combined inhibition of the ECM genes, VCAN, and ERK signaling may be more effective for preventing OSBPL2 loss induced colorectal tumor growth." (PMID 38267463, 2024). "OSBPL2 defect supported colorectal tumor growth and metastasis, which were suppressed by the ERK and PARP1 inhibitors SCH772984 and AG14361, respectively." (PMID 38267463, 2024). "We used a xenograft tumor model to assess the function of OSBPL2 in colorectal tumor growth in vivo." (PMID 38267463, 2024). "Otherwise, the level of Collagen I was evaluated based on the OSBPL2 defect in the in vivo model of colorectal tumor progression." (PMID 38267463, 2024). "The ERK inhibitor SCH772984 significantly alleviated colorectal tumor growth induced by OSBPL2 knockdown, with reduced average tumor weights and volumes by 41.19% and 39.24%, respectively." (PMID 38267463, 2024). "Most importantly, OSBPL2 inhibited colorectal tumor growth and distant metastasis, which were blocked by SCH772984 and AG14361." (PMID 38267463, 2024). "Additionally, OSBPL2 levels decreased in the primary colorectal tumors and liver metastases of patients with stage IV CRC, contrary to normal colorectal tissues." (PMID 38267463, 2024). "Briefly, this study illustrates that OSBPL2 defect collaborates with ECM Collagen I to promote colorectal tumor growth and metastasis through two independent pathways and provides the basis for appropriate therapy using ERK and PARP1 inhibitors to treat OSBPL2Low CRC." (PMID 38267463, 2024). "OSBPL2 was negatively correlated with VCAN, AREG, and EREG, whereas there was a positive correlation between VCAN, AREG, and EREG in colorectal tumors." (PMID 38267463, 2024). "Although OSBPL2 accelerated CRC cell proliferation without the ECM, the reduction of focal adhesion and FAK signaling led to a decrease in stable OSBPL2 OE cell-derived colorectal tumor growth in the Collagen I-rich TME." (PMID 38267463, 2024).
coronary artery disease (1 paper, 2025). "Additionally, OSBPL2 expression in peripheral blood mononuclear cells was reduced in patients with coronary artery disease as indicated by the GSE113079 dataset." (PMID 40349776, 2025).
hepatoma (1 paper, 2025). "Recent studies have uncovered a novel function of OSBPL2 as a regulator of the actin cytoskeleton in hepatoma cells (Huh7)." (PMID 40391522, 2025).
liver cancer (1 paper, 2023). An epithelial or non-epithelial malignant neoplasm that arises from the liver. "Taken together, these results imply that OSBPL2, OSBPL3, and OSBPL6 were potentially involved in liver cancer progression." (PMID 36918840, 2023). "The mRNA of OSBPL2, OSBPL3, and OSBPL8 were highly expressed while OSBPL6 was lowly expressed in liver cancer samples compared with normal samples." (PMID 36918840, 2023).
lung adenocarcinoma (1 paper, 2024). A carcinoma that arises from the lung and is characterized by the presence of malignant glandular epithelial cells. "By analyzing lung adenocarcinoma (LUAD) survival data, we found that high OSBP and OSBPL2 expressions are associated with significantly longer patient survivals, suggesting that downregulation of these genes is a signature of tumor malignancy." (PMID 37991810, 2024).
sensorineural hearing loss (1 paper, 2024). "In addition, OSBPL2 deletion may also lead to dysfunction of auditory cells by promoting excessive cholesterol biosynthesis and reactive oxygen species (ROS) production, indicating OSBPL2 deficiency may be implicated in the pathogenesis of sensorineural hearing loss." (PMID 39475791, 2024).
steatosis (1 paper, 2025). Increased lipid within the cytoplasm of cells. "Similarly, analysis of 2 independent human liver GEO data sets (GSE164760 and GSE33814) revealed that OSBPL2 mRNA expression was lower in steatosis and steatohepatitis liver tissues compared with normal controls." (PMID 40658787, 2025).
Tinnitus (1 paper, 2023). Tinnitus is an auditory perception that can be described as the experience of sound, in the ear or in the head, in the absence of external acoustic stimulation. "It is rather the accumulation of the protein OSBPL2 that leads to the engulfment of the autophagolysosomal system within OHC, which alters the physiology of OHC, leading to tinnitus and deafness." (PMID 38068993, 2023).
tumor (4 papers, 2012 to 2024). "The average weight and tumor volume of mice injected with OSBPL2 KD CRC cells increased by 169.41%, 100.48%, and 129.24% and 294.50%, 151.24%, and 202.70%, respectively." (PMID 38267463, 2024). "Overexpression of OSBPL2 restrained tumor metastasis to the lymph nodes and lungs." (PMID 38267463, 2024). "The results demonstrated that the protein expressions of OSBPL2 and OSBPL3 were elevated while OSBPL5, OSBPL6, OSBPL9, OSBPL10, and OSBPL11 were lowly expressed in tumor samples." (PMID 36918840, 2023). "As to the protein expression, OSBPL2 and OSBPL3 were significantly elevated and OSBPL5, OSBPL6, OSBPL9, OSBPL10, OSBPL11 were downregulated in tumor samples." (PMID 36918840, 2023).
cancer (1 paper, 2024). A tumor composed of atypical neoplastic, often pleomorphic cells that invade other tissues. "In agreement with the cell-line collection data, OSBP and OSBPL2 expressions positively correlate with the epithelial features of the given cancer tissue specimens." (PMID 37991810, 2024).
OSBPL2 also shares sentences with these, for which no sentence is quoted: colorectal cancer (2 papers); age-related hearing loss (1); breast carcinoma (1); dwarfism (1); metabolic disorders (1); non-small cell lung carcinoma (1); nonsyndromic hearing loss (1); synovial sarcoma (1).